RNU6-1060P (RNA, U6 small nuclear 1060, pseudogene)
Gene: Small nuclear RNA gene on chromosome 6 (23,124,981 to 23,125,087, reverse strand). Ensembl gene ENSG00000207394.
Homologues: Orthologues: chimpanzee U6 (100% identical), mouse Gm24423 (92% identical), mouse Gm22716 (91% identical), rat LOC120099391 (91% identical), rat LOC120097299 (88% identical), mouse Gm23142 (87% identical), mouse Gm26240 (86% identical), mouse Gm23926 (79% identical), rat LOC120097194 (74% identical). Paralogues in human: RNU6-116P (96% identical), RNU6-15P (96% identical), RNU6-19P (96% identical), RNU6-12P (95% identical), RNU6-13P (95% identical), RNU6-31P (95% identical), RNU6-32P (95% identical), RNU6-33P (95% identical), RNU6-41P (95% identical), RNU6-1 (94% identical), RNU6-17P (94% identical), RNU6-18P (94% identical), and 1286 more.